UNC93B1 (unc-93B1 regulator of TLR signaling)
Diseases named in the same sentence as UNC93B1 in open-access papers (continued):
Sharing a sentence is not in itself a finding about the gene and the disease.
lupus nephritis (1 paper, 2023). Glomerulonephritis in the context of systemic lupus erythematosus. "German Shorthaired Pointer (GSHP) dogs with a UNC93B1 gene mutation develop exfoliative cutaneous lupus erythematosus (ECLE) and kidney disease resembling lupus nephritis in humans." (PMID 37222157, 2023).
metabolic syndrome (1 paper, 2018). A cluster of metabolic risk factors for CARDIOVASCULAR DISEASES and TYPE 2 DIABETES MELLITUS. "Induction of metabolic syndrome, such as type 2 diabetes or nonalcoholic fatty liver disease, should be examined by using Tlr9d13/13 or Unc93b1−/− mice as further study." (PMID 29997629, 2018). "Despite the risk of infection by the reduction of TLR9 cleavage, TLR9 or Unc93B1 has a potential to be a target of intervention/prevention against metabolic syndrome." (PMID 29997629, 2018).
neuroblastoma (1 paper, 2021). Neuroblastoma (NB) is the most common solid, extracranial childhood tumor. "Unc93b1 RNA was readily detectable in the human neuroblastoma cell line SH-SY5Y, while no significant expression was found in the human microglial cell line HMC3." (PMID 34589086, 2021).
Salmonella Infections (1 paper, 2014). Infections with bacteria of the genus SALMONELLA. "Similarly, deficiency in Tlr9 and the processing molecule Unc93B1 significantly reduced the epithelial cell response to Salmonella infection." (PMID 25210785, 2014).
Sepsis (1 paper, 2011). Sepsis is defined as life-threatening organ dysfunction caused by a dysregulated host response to infection. "Ppargc1a/b activation did not require NF-kβ, but did require an interferon response factor (IRF), because neither gene was activated in IRF-3/7 double-knockout mice in sepsis, but both were activated normally in Unc93b1-deficient (3d) mice." (PMID 21966468, 2011).
Stroke (1 paper, 2012). Sudden impairment of blood flow to a part of the brain due to occlusion or rupture of an artery to the brain. "A number of new stroke-genes related to T- and dendritic cell activation and differentiation including Cd 8a, Tmem176b, Unc93b1, Vamp8, and Wipf1 also displayed persistent upregulation." (PMID 23251410, 2012).
infection (18 papers, 2010 to 2025). The state of being infected such as from the introduction of a foreign agent such as serum, vaccine, antigenic substance or organism. "Unexpectedly, S. pyogenes infection of Unc93b1-deficient BMDMs resulted in comparable TNF production as infection of WT cells." (PMID 25756897, 2015). "Lack of TLR2 strongly impaired cytokine production by cDCs in the very early phase (i.e. 2.5 h post infection), whereas this phase appeared normal in Unc93b1-deficient cells." (PMID 25756897, 2015). "We observed an increased susceptibility of both TLR2- and Unc93b1-deficient animals to infection compared to WT controls." (PMID 25756897, 2015). "We found that the triple deficient ‘3d’ mice, which lack functional UNC93B1, are hyper-susceptible to infection with Toxoplasma gondii." (PMID 20865117, 2010). "Nevertheless, animals bearing UNC93B1 mutation succumbed to infection as a result of unchecked tachyzoite replication, similar to IFNγ−/− mice." (PMID 20865117, 2010). "Of note, enhanced IL-6 secretion in Unc93b1 mutated vs. Tlr13-deficient BMDMs was observed after infection with MOI 50, potentially by compensatory upregulation of TLR2 following its stimulation to counterbalance the loss of all endosomal TLRs under high bacterial load." (PMID 30846984, 2019). "A more recent study showed that the three nucleic acid sensing TLRs, TLR3, 7 and 9, are crucial for a protective response against L. major infection, as mice which lacked all of these functional TLRs (i.e. TLR3/TLR7/TLR9−/− or UNC93B1−/− mice) were highly susceptible to infection." (PMID 27716391, 2016). "Nevertheless, infection of reciprocal bone marrow chimeras between wild-type and 3d mice with T. gondii demonstrated a primary role of hemopoietic cell lineages in the enhanced susceptibility of UNC93B1 mutant mice." (PMID 20865117, 2010). "Three novel genes—Limd2, Ptms, and Unc93b1—were also identified to correlate with MTB cellular infection." (PMID 39813329, 2025). "At the same time, histopathological examination 24 h post infection revealed more severe lesions in Unc93b1 mutant mice with an elevated bacterial load and more inflammatory cells invading into deeper layers of the lesions." (PMID 30846984, 2019). "Together, our data demonstrate a failure in early recognition of S. pyogenes ATCC12344 in Unc93b1 mutant mice, leading to a reduced containment of S. pyogenes in the course of infection with subsequent spread and systemic inflammation." (PMID 30846984, 2019). "We therefore assessed these parameters in BMDMs and BMDCs from WT, Unc93b1 3d, and Tlr13−/− mice upon infection with S. pyogenes ATCC12344 in vitro." (PMID 30846984, 2019). "Infection of UNC93B1 mutant mice revealed reduced production of systemic and liver proinflammatory cytokines including IFN-α, IFN-γ, IL-12 and TNF-α when compared to wild-type." (PMID 22723955, 2012). "Our studies show that proinflammatory cytokine production after early infection with MCMV is dependent on UNC93B1." (PMID 22723955, 2012). "Confocal microscopy revealed that after infection, there was an enrichment of UNC93B1 around the internalized parasites in cell lines that expressed the wild-type, but not the mutated/non-functional protein." (PMID 20865117, 2010). "Nevertheless, we provide evidence of a critical role of UNC93B1 in mediating IL-12 as well as early IFNγ production during acute infection with T. gondii." (PMID 20865117, 2010). "During the early phase of infection, Unc93b1 mutant mice displayed significantly decreased systemic IL-6 levels compared to their WT controls, indicative of an insufficient recognition of S. pyogenes by the innate immune cells, thus potentially favoring systemic dissemination." (PMID 30846984, 2019). "However, in Unc93b1 mutant, and Tlr13−/− BMDMs production of IL-6 and TNFα upon infection with S. pyogenes ATCC12344 and M49 was almost abrogated at lower MOIs, indicating a non-redundant role of RNA/TLR13 recognition at low bacterial burden." (PMID 30846984, 2019).
infection (continued). "Consistent with the initial ISG screen, a dose-response to infection revealed that MYD88 and UNC93B1 reduced Lm infectivity (defined as the MOI of Lm required to achieve 50% cellular infection during the course of 8 hours) by 9.7-fold and 5.7-fold compared to firefly luciferase control." (PMID 28002492, 2016). "Considering the highly redundant functions of the TLR2- and Unc93b1-mediated sensing pathways in vitro, we asked whether these pathways were redundant during infection of mice." (PMID 25756897, 2015). "Considering the potential of endosomal TLR signals to induce proinflammatory cytokine expression, UNC93B1 deficient 3d mice were first assessed for systemic IFN-α, IFN-γ, IL-12 and TNF-α production during early infection with a moderate (5×104 PFU) dose of MCMV." (PMID 22723955, 2012). "In addition, a strongly reduced cytokine production has been observed in MyD88-deficient mice at 20 h post infection, while cytokine levels were significantly increased in Unc93b1 mutant mice 24 h post infection, indicating the presence of UNC93B1-independent, but MyD88-dependent pathways." (PMID 30846984, 2019). "Secretion of IL-10 in response to infection with the parental strain was mostly TLR2-dependent, while IL-10 secretion in response to lysozyme-sensitive strains was dependent on TLR2 and Unc93b1." (PMID 32634175, 2020). "Thus, chronic treatment with Class G INH-ODNs may potentially lead to enhanced susceptibility to infection, even though the phenotype of mutated mice including those lacking the functional transporter molecule UNC93B1 is relatively mild." (PMID 20490286, 2010). "Inhibition of TLR2 in WT BMDMs only slightly attenuated IL-6 production upon infection with S. pyogenes ATCC12344, whereas cytokine production was completely abolished in Unc93b1 mutant cells and strongly attenuated in Tlr13−/− cells upon additional blocking of TLR2." (PMID 30846984, 2019). "UNC93B1 can facilitate trans-location of TLR (TLR3, TLR7 and TLR9) from the endoplasmic reticulum to the Golgi and mediates the host immune responses to infection with murine cytomegalovirus, as well as several intracellular protozoan parasites." (PMID 29530077, 2018). "Mice lacking TLR12, the TLR-induced adaptor proteins MyD88 or UNC93B1 and the inflammasome proteins NLRP3 or ASC all exhibit a high susceptibility to Toxoplasma infection during the early stage of the infection due to an impaired innate immune response." (PMID 28701773, 2017). "Here, we tested the 3d mouse, which has a non-functional UNC93B1, to evaluate the combined role of nucleotide sensing TLRs in controlling initial activation of innate immunity and host resistance to infection with T. gondii." (PMID 20865117, 2010). "IEIs of TLR3-, IRF7-, UNC93B1-, TICAM1-, TBK1-, and interferon alpha and beta receptor subunit 1 (IFNAR1)-dependent type I interferon immunity have been described to underlie life-threatening COVID-19 pneumonia in patients with no prior severe infection." (PMID 37559153, 2023). "Furthermore, upon in vitro infection the rate of tachyzoite replication was enhanced in non-activated macrophages carrying mutant UNC93B1 as compared to wild type gene." (PMID 20865117, 2010). "Finally, infectious challenge of reciprocal chimeras demonstrated that expression of wild type, functional UNC93B1, in the hemopoietic, but not in the non-hemopoietic compartment was necessary for host resistance to infection with T. gondii." (PMID 20865117, 2010). "Knock-down of RIG-I, MDA-5, UNC93B1, MAVS or STING in THP1/CD169 macrophages did not impact infection efficiency of SARS-CoV-2, as shown by RT-qPCR analysis of viral gRNA and sgRNAs in each cell line." (PMID 36279285, 2022). "Upon infection of MDMs with LaiΔenvGFP/G, we observed downregulation of IP-10 and IFN-β mRNA expression upon MDA5 knockdown, but not upon knockdown of either RIG-I or UNC93B1." (PMID 40493408, 2025).
tumor (6 papers, 2017 to 2026). "UNC93B1 was robustly upregulated in tumor tissues across independent datasets (TCGAxGTEx, bulk RNA-seq), a finding corroborated at the protein level by HPA and CPTAC data (P < 0.01)." (PMID 41716413, 2026). "Consistently, in vivo xenograft experiments demonstrated that UNC93B1 silencing markedly impeded tumor growth, concomitant with reduced UNC93B1 protein and enhanced STING pathway activation." (PMID 41716413, 2026). "Pseudotime analysis indicated that UNC93B1 expression escalates along tumor progression trajectories." (PMID 41716413, 2026). "UNC93B1 promotes tumour growth by regulating the secretion level of granulocyte macrophage colony-stimulating factor in human oral cancer." (PMID 33113804, 2020). "These classical innate immune cells (macrophages, DCs, neutrophils, Basophils, Eosinophils, Mast cells and NK cells) offers an alternative immunotherapeutic option to attack tumor cells, and targeting TLRs or metabolism signaling dysregulated by UNC93B1 might be an effective treatment too." (PMID 36741319, 2023). "The physical interaction between UNC93B1 and TLRs is essential for immune TLR signalling, a cascade leading to tumour evasion from immune surveillance." (PMID 33113804, 2020). "The amplification of genes such as COL5A1, IDO1, and GOLIM4 were in accordance with their higher expression in tumor samples, whereas no significant change of protein or phosphorylation levels was observed for genes with genomic amplification, such as CD4, CD7, LIME1, UNC93B1, C1S, C1R, or C8G." (PMID 34400640, 2021).
cancer (3 papers, 2020 to 2023). A tumor composed of atypical neoplastic, often pleomorphic cells that invade other tissues. "Pan-cancer analysis revealed that UNC93B1 was widely and highly expressed in most malignancies, especially in AML (p < 0.001)." (PMID 36741319, 2023). "The expression levels of CXCL12, THBS1, PPBP, GZMB, CD74, and UNC93B1 were higher in the cancer group than in the normal group." (PMID 36211454, 2022). "We found that 30 of these genes which included Nckap1l, Ncf1, Pla2g15, Unc93b1, Lrrc33, Rgs10, Gmfg, Rbm25, C3ar1, Ccdc88b, Fam105a, Gng11, Phc1, Rasa4, Dag1, Tyrobp, Tmsb4x, Cfp, Prkd1, Gp49a, Trem2, C1qc, Lyz2, Igfbp7, Rab30, Cxcl16, Egfl7, Ube2r2, Pltp, and Cfb, showed a relation with cancer." (PMID 32812032, 2020).
UNC93B1 also shares sentences with these, for which no sentence is quoted: chilblain lupus (2 papers); rheumatoid arthritis (2); asthma (1); bacterial infections (1); Childhood onset (1); chronic leukemia (1); colon tumor (1); cutaneous lupus erythematosus (1); cytomegalovirus infection (1); diffuse large B-cell lymphoma (1); enterovirus infections (1); eosinophilia (1); familial Mediterranean fever (1); Gliosis (1); glomerulonephritis (1); juvenile arthritis (1); kidney disease (1); lupus erythematosus (1); melanoma (1); metabolic disease (1); nephritis (1); Neurodegeneration (1); nonalcoholic fatty liver disease (1); oral cancer (1); oral squamous cell carcinomas (1); pancreatic cancer (1); pneumonia (1); primary immunodeficiency (1); type 2 diabetes (1).